WNK3 (WNK lysine deficient protein kinase 3)
Diseases named in the same sentence as WNK3 in open-access papers:
WNK3 is named in the same sentence as 37 diseases in open-access papers, as found by Europe PMC text mining. Sharing a sentence is not in itself a finding about the gene and the disease. The quoted sentences say what the papers report.
glioma (6 papers, 2012 to 2022). A benign or malignant brain and spinal cord tumor that arises from glial cells (astrocytes, oligodendrocytes, ependymal cells). "Knocking down WNK3 can inhibit the invasion of glioma cell lines by regulating the epithelial-mesenchymal transition, especially in hypoxic microenvironments." (PMID 35647198, 2022). "Recent reports suggested that WNK3 stimulates glioma invasion by regulating cell volume, meanwhile another study implied that WNK3 plays important role in the response of ischemia-induced brain damage." (PMID 34513083, 2021). "To investigate if WNK3 was expressed in glioma cells, we first assessed three widely used glioma cell lines: U87, U373, and U251." (PMID 34513083, 2021). "To explore the mechanism by which WNK3 regulates glioma cell proliferation, we measured the expression of the proliferation-associated protein CyclinD1." (PMID 34513083, 2021). "The work presented in this paper focuses on the role of WNK3 gene in glioma invasion under hypoxic conditions." (PMID 34513083, 2021). "Our results revealed that WNK3 expression was more prominent in high-grade glioma than low-grade glioma." (PMID 34513083, 2021). "WNK3 expression was up-regulated in U87 cells when cultured in a hypoxic environment in addition; WNK3 knockdown inhibited the invasion of U87 glioma cells by regulating the EMT, especially under hypoxic conditions." (PMID 34513083, 2021). "In the present study, we discovered that WNK3 was up-regulated during hypoxic conditions in the U87 glioma cell line." (PMID 34513083, 2021). "The results of the experiment indicated that WNK3 played an important role in the hypoxic response of glioma cells and exerted a widespread influence on the invasion of glioma cells during both normoxia and hypoxia." (PMID 34513083, 2021). "Compared to normal human astrocytes, we detected a lower expression level of WNK3 protein in all three glioma cell lines." (PMID 24555568, 2014). "This suggests an important link between the activation of WNK3 by Akt as well as changes in the activity of ion transport systems in glioma cells." (PMID 22570591, 2012). "In addition, we used immunohistochemical staining to evaluate the expression of WNK3 in 63 glioma tissue samples." (PMID 34513083, 2021). "We found that WNK3 was expressed in different grades of glioma tissues." (PMID 34513083, 2021). "In this study, we demonstrated that hypoxia can up-regulate WNK3 expression in U87 glioma cells." (PMID 34513083, 2021). "However, little is known about the role WNK3 plays in the hypoxic response of glioma and its impact on the EMT." (PMID 34513083, 2021). "We also evaluated WNK3 expression levels in glioma samples by immunohistochemistry analysis." (PMID 34513083, 2021). "It is reasonable for us to speculate that WNK3 may also be involved in enhancing the invasiveness of glioma in hypoxic conditions." (PMID 34513083, 2021). "Moreover, the TGF-β pathway is one of the most important pathways involved in the EMT; further investigation into the mechanisms by which WNK3 influences the EMT in glioma should involve examination of these pathways." (PMID 34513083, 2021). "All these data testified the speculation that WNK3 was involved in the hypoxic response in glioma cells." (PMID 34513083, 2021). "The discrepancy of these findings on WNK1 and WNK3 expression may result from heterogeneity of the glioma cells." (PMID 24555568, 2014). "Also, the reduced expression of WNK3 by shRNA diminished the ability of glioma cells to migrate in vitro." (PMID 22570591, 2012). "Importantly, we found that WNK3 can promote glioma invasion by regulating the EMT process." (PMID 34513083, 2021). "In addition, WNK3 functions as a “bad boy” because it promotes invasion in glioma." (PMID 34863180, 2021). "Our data confirmed that WNK3 was involved in hypoxia-induced EMT and consequently regulate glioma invasive." (PMID 34513083, 2021).
glioma (continued). "WNK3 expression was significantly higher in high-grade (III and IV) gliomas than in low-grade (I and II) gliomas." (PMID 34513083, 2021). "Furthermore, we found that WNK3 expression was more prevalent in high-grade (III and IV) gliomas than in low-grade (I and II) gliomas." (PMID 34513083, 2021). "The precise mechanisms by which WNK3 regulates the EMT in glioma are not clear." (PMID 34513083, 2021).
ischemic stroke (5 papers, 2016 to 2022). A stroke disorder caused by obstruction of blood flow to the brain, due to thrombotic (local blood clot formation) or embolic (due to a blood clot or other material traveling from another site) event. "Certainly, the upstream WNK3-SPAK/OSR1 pathway regulation of NKCC1 activity coupled with inhibition of KCC3 is implicated in the pathology of ischemic stroke." (PMID 33513812, 2021). "WNK3-SPAK/OSR1 cation-chloride cotransporter pathway has been reported as a potential therapeutic target in ischemic stroke as knocking down SPAK/OSR1 improved neuroprotection." (PMID 35328807, 2022). "Compared to WT mice, WNK3 KO and SPAK KO (or SPAK heterozygous) mice showed more than a 50% reduction in infarct volume and associated cerebral edema after ischemic stroke." (PMID 31165006, 2019). "In a recent experimental ischemic stroke study, WNK3 KO mice displayed significantly decreased cerebral swelling, axonal demyelination, and infarct volume as well as accelerated neurobehavioral recovery, compared to WT mice." (PMID 31165006, 2019). "Increased BBB permeability was detected in WNK3 WT mice 3 days after ischemic stroke, as reflected by greatly increased IgG accumulation in ipsilateral peri-lesional cortices (p < 0.05)." (PMID 27782176, 2016). "In addition, we recently demonstrated that WNK3 KO mice exhibit reduced endothelial and perivascular cytotoxic edema of astrocytes following post-ischemic stroke." (PMID 33513812, 2021). "Generally, deletion of the WNK3-SPAK kinase complex significantly produced less cytotoxic edema, less demyelination, and improved post-ischemic stroke neurological outcomes in the transgenic mice." (PMID 33513812, 2021). "The deletion of the WNK3-SPAK kinase complex in mice improves radiographic and clinical outcomes in malignant cerebral edema after ischemic stroke." (PMID 33588817, 2021). "Accordingly, WNK3-SPAK inhibition prevents acute cell swelling in response to osmotic stress, and ameliorates brain swelling after ischemic stroke." (PMID 27782176, 2016).
Stroke (4 papers, 2016 to 2025). Sudden impairment of blood flow to a part of the brain due to occlusion or rupture of an artery to the brain. "Inhibition of WNK3 is reportedly neuroprotective in stroke and intracerebral hemorrhage, but has a deleterious effect on neurons after traumatic brain injury." (PMID 39633006, 2025). "As such, further research will need to elucidate the distinction between the role of AQP4 and WNK3 in cerebral edema and stroke." (PMID 33513812, 2021). "Therefore, bumetanide treatment had an effect similar to that of GABAA receptor antagonists and WNK3 knockout mice, which may promote functional recovery after stroke via neuroprotection." (PMID 38850525, 2024). "However, transgenic KO of WNK3, abridged ischemia-mediated SPAK/OSR1-NKCC1 phosphorylation and displayed reduced cerebral edema, axonal demyelination, and infarct volume, as well as improved post-stroke neurological recovery when compared to WT mice." (PMID 33513812, 2021).
schizophrenia (3 papers, 2011 to 2021). A major psychotic disorder characterized by abnormalities in the perception or expression of reality. "However, they found overexpression of OXSR1 and WNK3 transcripts in schizophrenia." (PMID 35069119, 2021). "Previous studies found that messenger RNA (mRNA) expression levels of "Oxidative Stress Response kinase" (OXSR1) and "With No lysine Kinase 3" (WNK3) were increased in schizophrenia in the DLPFC." (PMID 25826365, 2015). "Interestingly, KCC2 and NKCC1 transcript levels were not altered in subjects with schizophrenia; however, transcripts for two kinases (OXSR1 and WNK3) that strongly regulate KCC2 and NKCC1 activity in opposite directions, are overexpressed in schizophrenia." (PMID 21904685, 2011).
Anxiety (2 papers, 2022 to 2025). Intense feelings of nervousness, tension, or panic often arise in response to interpersonal stresses. "In addition, locomotion and anxiety levels are unaffected by the loss of WNK3 function." (PMID 36311015, 2022). "The time spent in the center of the arena and total distance traveled within a period of 5 min in an open-field apparatus were not significantly different between WNK3 KO and WT littermates, indicating no changes in anxiety levels and locomotor activities, respectively." (PMID 36311015, 2022).
ischemia (2 papers, 2021 to 2022). A hypoperfusion of the BLOOD through an organ or tissue caused by a PATHOLOGIC CONSTRICTION or obstruction of its BLOOD VESSELS, or an absence of BLOOD CIRCULATION. "For example, loss of WNK3 may reduce ischemia-associated brain damage, whereas mutations in WNK1 and WNK4 disrupt renal salt uptake to induce pseudohypoaldosteronism type II (PHAII)." (PMID 35179207, 2022).
lung carcinoma (2 papers, 2022 to 2023). "To finally assess the clinical implications of WNK3 in tumor immune resistance, we compared the prognosis of lung cancer patients with WNK3-high and WNK3-low expression tumors." (PMID 36357569, 2022). "Lung cancer patients with high WNK3 expression showed shorter survival, and high WNK3 expression could be a poor prognostic marker of cancer." (PMID 36357569, 2022). "Our data collectively indicated that WNK3 and SIK3 were positive PD-L1 regulators in lung cancer cells." (PMID 36357569, 2022).
autism (1 paper, 2024). Persistent deficits in social interaction and communication and interaction as well as a markedly restricted repertoire of activity and interest as well as repetitive patterns of behavior. "WNK3 was reported to be partially deleted in two brothers with autism, ID, and cleft lip/palate and a maternally inherited microdeletion." (PMID 38572415, 2024).
brain ischemia (1 paper, 2020). Diminished or absent blood supply to the brain caused by obstruction (thrombosis or embolism) of an artery resulting in neurologic damage. "Middle cerebral artery occlusion (MCAO) was performed to produce brain ischemia, a maneuver that induces cerebral edema, in wild type (WT), WNK3–/–, and SPAK–/– mice." (PMID 33192599, 2020). "Phosphorylation levels of KCC3 and NKCC1 in brain homogenates of WNK3–/– mice after brain ischemia were decreased compared to those in wild type mice." (PMID 33192599, 2020).
colon adenocarcinoma (1 paper, 2022). "To evaluate the functional role of the WNK3/PD-L1 axis in an in vivo setting, we used the MC38 syngeneic colon adenocarcinoma mouse model, one of the commonly used mouse xenograft models responsive to anti-PD-1 or anti-PD-L1 monotherapy." (PMID 36357569, 2022).
colon cancer (1 paper, 2022). "The human colon cancer cell line HCT116 also recapitulated the WNK3/PD-L1 relationship, suggesting that this axis might be functional in cancers other than NSCLC." (PMID 36357569, 2022).
diabetes (1 paper, 2024). "A high-glucose medium increases WNK3 signaling in VSMCs undergoing mitosis, which could explain the increased thickness of aortic tissues in subjects with diabetes." (PMID 38674024, 2024).
edema (1 paper, 2016). An abnormal accumulation of fluid beneath the skin, or in one or more cavities of the body. "Genetic inhibition of WNK3-SPAK signaling in the MCAO model also ameliorated two cell swelling-associated components of ischemic cerebral edema: perivascular cytotoxic edema of astrocytes and endothelial cell cytotoxic edema (both contributing to BBB breakdown)." (PMID 27782176, 2016).
Hyperglycemia (1 paper, 2024). An increased concentration of glucose in the blood. "Hyperglycemia and hyperinsulinemia increase WNK3 signaling in VSMCs undergoing mitosis, which may explain the increased thickness of aortic tissues in subjects with T2D." (PMID 38674024, 2024).
sarcoma (1 paper, 2022). A usually aggressive malignant neoplasm of the soft tissue or bone. "As analyzed by Kaplan–Meier survival time analysis in a large collection of 230 cases, patients suffering from sarcoma with a high expression of WNK3 died significantly earlier than sarcoma patients with a low WNK3 expression (p = 0.001)." (PMID 35163434, 2022). "A Kaplan–Meier survival analysis of the tumors deposited in the cBioPortal database revealed that high WNK3 mRNA expression was significantly correlated with shorter survival of sarcoma patients." (PMID 35163434, 2022). "This hypothesis warrants further detailed investigations to clarify whether WNK3 may hold a prognostic or therapeutic significance in sarcomas, as well as in carcinomas and hematopoietic malignancies." (PMID 35163434, 2022). "This implies that inhibition of WNK3 by CSA might contribute to better survival chances of sarcoma patients." (PMID 35163434, 2022).
cancer (9 papers, 2013 to 2024). A tumor composed of atypical neoplastic, often pleomorphic cells that invade other tissues. "WNK3 inhibition suppressed PD-L1 expression in cancer cells, thereby increasing their susceptibility to CD8+ T cells, whereas in immune cells, it facilitated antitumorigenic cytokine secretion by CD8+ T cells." (PMID 36357569, 2022). "While identifying WNK3 inhibition as a route towards restoring the anti-cancer activity of T cells, the research also revealed details of the molecular signaling pathways that allow WNK3 to affect PD-L1 production." (PMID 36357569, 2022). "Consistently, WNK3 expression was significantly associated with poor overall survival in colon (GSE39582) and gastric (GSE62254) cancer cohorts." (PMID 36357569, 2022). "Drugs that inhibit WNK3 can now be investigated as a new approach to treating cancer, due to their effects on both immune system cells and cancer cells." (PMID 36357569, 2022). "Among the novel PD-L1 enhancers, we demonstrated that WNK3, a less characterized protein in cancer, is necessary and sufficient for the transactivation of PD-L1 through its kinase activity in JNK-dependent but IFN-γ/STAT3-independent mechanisms." (PMID 36357569, 2022). "WNK3 perturbation increased cancer cell death in cancer cell–immune cell coculture conditions and boosted the secretion of cytokines and cytolytic enzymes, promoting antitumor activities in CD4+ and CD8+ T cells." (PMID 36357569, 2022). "Taken together, these results revealed that WNK3, the downstream target gene of miR-130a-3p, modulated the radiosensitivity of both A549 and H460 cancer cells." (PMID 34863180, 2021). "More specifically, WNK3, an important factor in many pathways, functions as an accelerator of cancer." (PMID 34863180, 2021). "In the MPNST, aside from the NF1 mutation, other mutations in cancer‐associated genes such as EHBP1 and WNK3 were identified." (PMID 26432421, 2015). "Our findings highlight that WNK3 inhibition might serve as a potential therapeutic strategy for cancer immunotherapy through its concurrent impact on cancer cells and immune cells." (PMID 36357569, 2022). "Next, we examined whether shRNA-mediated depletion of WNK3 could sensitize cancer cells to immune cell attack." (PMID 36357569, 2022). "Before evaluating WNK3 and SIK3, we first confirmed that H460 and H2009 cells stably expressing shPD-L1 exhibited increased susceptibility (decreased cancer cell viability) to IL-2 and anti-CD3-activated peripheral blood mononuclear cells (PBMCs)." (PMID 36357569, 2022). "The WNK3/PD-L1 axis is preserved across various cancer types and species." (PMID 36357569, 2022). "For example, Wnk3, a kinase that plays an role in the regulation of ion transporters in both the kidney and extrarenal tissues, has also been shown to play a role in various pathologies, like cancer and to developmental processes like cardiovascular and neuronal development." (PMID 34193044, 2021). "The next question we asked ourselves was, how relevant WNK3 and the other four top inhibited targets (EIF2AK2, p38γ, PAK1, and RPS6KA3) are to cancer." (PMID 35163434, 2022). "To elucidate the signaling pathways involved in WNK3-mediated PD-L1 regulation, we investigated several key signaling pathways, including JNK/c-JUN, ERK, p38, AKT, NF-κB, and JAK/STAT, which regulate PD-L1 transcription in cancer cells." (PMID 36357569, 2022). "Targeted inhibition of expression SNRPN, WNK3 and FAM3B may therefore constitute a potential therapeutic strategy for HCC and more generally for other cancers." (PMID 34006907, 2021). "WNK3 expression had no influence on cancer patients affected with other tumor types." (PMID 35163434, 2022). "Notably, WNK3 inhibition did not affect MHC class I protein expression, indicating that it did not impair antigen presentation by cancer cells to CD8+ T cells." (PMID 36357569, 2022).
tumor (7 papers, 2012 to 2024). "Inhibiting the activity of the protein WNK lysine deficient protein kinase 3 (WNK3) boosts anti-tumor immunity by suppressing the production of another protein (PD-L1) whose activity promotes the programmed cell death of immune system T cells." (PMID 36357569, 2022). "To address the first question, we correlated the microarray-based mRNA expression of the 5 CSA targets (EIF2AK3, MAPK12/p38γ, PAK1, RPS6KA3, and WNK3) in a panel of 60 tumor lines of the NCI, USA, with 83 standard anticancer agents." (PMID 35163434, 2022). "Tests in mice confirmed that WNK3 inhibition can suppress tumor growth." (PMID 36357569, 2022). "Furthermore, exposure of GB cells to EGF, a factor that promotes migration and invasion of normal and tumor cells, induces phosphorylation (activation) of NKCC1 through PI3K-Akt-WNK3 pathway." (PMID 22570591, 2012).
neurological disorders (1 paper, 2021). "WNK3 possibly affects neuronal somatic and synaptic properties by modulating KCC2 activity, resulting in abnormal activity patterns that may underlie psychiatric and neurological disorders." (PMID 34858138, 2021).
WNK3 also shares sentences with these, for which no sentence is quoted: infection (36 papers); dementia (2); Hypertension (2); ascorbic acid deficiency (1); breast carcinoma (1); COVID-19 (1); endometriosis (1); epilepsy (1); fungal infection (1); Hyperinsulinemia (1); Intellectual disability (1); intracerebral hemorrhage (1); lung adenocarcinoma (1); melanoma (1); papillary renal cell carcinoma (1); prostate carcinoma (1); renal fibrosis (1); tuberculosis (1); virus infection (1).